PDGFRA (platelet derived growth factor receptor alpha)
Description:
Tyrosine-protein kinase that acts as a cell-surface receptor for PDGFA, PDGFB and PDGFC and plays an essential role in the regulation of embryonic development, cell proliferation, survival and chemotaxis. Depending on the context, promotes or inhibits cell proliferation and cell migration. Plays an important role in the differentiation of bone marrow-derived mesenchymal stem cells. Required for normal skeleton development and cephalic closure during embryonic development. Required for normal development of the mucosa lining the gastrointestinal tract, and for recruitment of mesenchymal cells and normal development of intestinal villi. Plays a role in cell migration and chemotaxis in wound healing. Plays a role in platelet activation, secretion of agonists from platelet granules, and in thrombin-induced platelet aggregation. Binding of its cognate ligands - homodimeric PDGFA, homodimeric PDGFB, heterodimers formed by PDGFA and PDGFB or homodimeric PDGFC -leads to the activation of several signaling cascades; the response depends on the nature of the bound ligand and is modulated by the formation of heterodimers between PDGFRA and PDGFRB. Phosphorylates PIK3R1, PLCG1, and PTPN11. Activation of PLCG1 leads to the production of the cellular signaling molecules diacylglycerol and inositol 1,4,5-trisphosphate, mobilization of cytosolic Ca(2+) and the activation of protein kinase C. Phosphorylates PIK3R1, the regulatory subunit of phosphatidylinositol 3-kinase, and thereby mediates activation of the AKT1 signaling pathway. Mediates activation of HRAS and of the MAP kinases MAPK1/ERK2 and/or MAPK3/ERK1. Promotes activation of STAT family members STAT1, STAT3 and STAT5A and/or STAT5B. Receptor signaling is down-regulated by protein phosphatases that dephosphorylate the receptor and its down-stream effectors, and by rapid internalization of the activated receptor.
Synonyms: PDGFR-2; CD140a; PDGFR2; GAS9
Tractability: Small molecule: an approved drug acts on it; a structure with a bound ligand is known; a high-quality ligand is known; it belongs to a druggable protein family. Antibody: an approved drug acts on it; UniProt places it where antibodies can reach, with high confidence; its Gene Ontology location is reachable by antibodies, with high confidence; UniProt predicts a signal peptide or a membrane-spanning region. PROTAC: UniProt records ubiquitination sites on it; ubiquitination databases record sites on it; its protein half-life has been measured; a small molecule that binds it is known. Other modalities: an approved drug acts on it.
Target class: TK protein kinase group; Kinase; Tyrosine protein kinase PDGFR family; Protein Kinase; Enzyme
Chemical probes: AC710, AMUVATINIB, PD084121, PD134475, PD134476, PD134477, PD134478, PD134479, PD134480
Gene: Protein-coding gene on chromosome 4 (54,229,130 to 54,298,246, forward strand). Ensembl gene ENSG00000134853.
Subcellular location: Cell membrane; Cell projection, cilium; Golgi apparatus
Subcellular location (Human Protein Atlas): Cell Junctions; Nucleoplasm; Plasma membrane; Cytosol; Nuclear bodies; Primary cilium
Pathways (Reactome):
Disease: Constitutive Signaling by Aberrant PI3K in Cancer; Imatinib-resistant PDGFR mutants; PDGFR mutants bind TKIs; Regorafenib-resistant PDGFR mutants; Signaling by PDGFRA extracellular domain mutants; Signaling by PDGFRA transmembrane, juxtamembrane and kinase domain mutants; Sorafenib-resistant PDGFR mutants; Sunitinib-resistant PDGFR mutants
Signal Transduction: Downstream signal transduction; PI5P, PP2A and IER3 Regulate PI3K/AKT Signaling; PIP3 activates AKT signaling; RAF/MAP kinase cascade; Signaling by PDGF
Gene Ontology:
Molecular function: phospholipase C activator activity; platelet-derived growth factor alpha-receptor activity; platelet-derived growth factor binding; platelet-derived growth factor receptor binding; protein binding; protein homodimerization activity; protein kinase activity; transmembrane receptor protein tyrosine kinase activity; vascular endothelial growth factor binding; vascular endothelial growth factor receptor activity; ATP binding; protein tyrosine kinase activity; protein-containing complex binding
Biological process: cellular response to reactive oxygen species; negative regulation of platelet activation; peptidyl-tyrosine phosphorylation; platelet aggregation; platelet-derived growth factor receptor signaling pathway; platelet-derived growth factor receptor-alpha signaling pathway; positive regulation of calcium-mediated signaling; positive regulation of cell migration; positive regulation of cell population proliferation; positive regulation of cell proliferation by VEGF-activated platelet derived growth factor receptor signaling pathway; positive regulation of chemotaxis; positive regulation of ERK1 and ERK2 cascade; positive regulation of fibroblast proliferation; protein autophosphorylation; regulation of mesenchymal stem cell differentiation; cardiac myofibril assembly; cell activation; cell migration; cell surface receptor protein tyrosine kinase signaling pathway; embryonic cranial skeleton morphogenesis; embryonic digestive tract morphogenesis; embryonic skeletal system morphogenesis; luteinization; metanephric glomerular capillary formation; peptidyl-tyrosine autophosphorylation; and 6 more
Cellular component: membrane; plasma membrane; platelet-derived growth factor receptor-ligand complex; protein-containing complex; cilium; cytoplasm; endoplasmic reticulum membrane; Golgi apparatus; nucleus; receptor complex; cell surface; external side of plasma membrane; microvillus
Genetic constraint (gnomAD): Loss-of-function variants: 16 observed, 92.2 expected, observed/expected ratio (o/e) 0.17, 90% interval 0.12 to 0.26. The upper end of that interval is the gene's LOEUF score, 0.26, which puts it in group 1 of 6, group 1 being the genes least tolerant of losing a copy. Missense variants: 886 observed, 1,212 expected, observed/expected ratio (o/e) 0.73, 90% interval 0.69 to 0.77. Synonymous variants: 405 observed, 453.71 expected, observed/expected ratio (o/e) 0.89, 90% interval 0.82 to 0.97.
Gene-disease validity (ClinGen):
ClinGen rates the evidence that PDGFRA causes each of these diseases.
gastrointestinal stromal tumor (autosomal dominant): Definitive.
congenital heart disease (autosomal dominant): Limited. A heart disease that is present at birth.
Cancer hallmarks: invasion and metastasis (promotes); escaping programmed cell death (suppresses); angiogenesis (suppresses); suppression of growth (promotes); angiogenesis (promotes); proliferative signalling (promotes)
Homologues: Orthologues: chimpanzee PDGFRA (99% identical), macaque PDGFRA (98% identical), dog PDGFRA (96% identical), pig PDGFRA (96% identical), mouse Pdgfra (92% identical), rat Pdgfra (91% identical), guinea pig PDGFRA (91% identical), tropical clawed frog pdgfra (75% identical), zebrafish pdgfra (61% identical), rabbit PDGFRA (60% identical). Paralogues in human: PDGFRB (44% identical), KIT (31% identical), CSF1R (29% identical), FLT1 (29% identical), KDR (29% identical), FLT4 (28% identical), FLT3 (27% identical), FGFR1 (21% identical), FGFR2 (20% identical), FGFR3 (19% identical), FGFR4 (19% identical), ROS1 (17% identical), and 41 more.
Diseases named in the same sentence as PDGFRA in open-access papers:
PDGFRA is named in the same sentence as 493 diseases in open-access papers, as found by Europe PMC text mining. Sharing a sentence is not in itself a finding about the gene and the disease. The quoted sentences say what the papers report.
gastrointestinal stromal tumor (325 papers, 2005 to 2026). "Imatinib is the first-line treatment for advanced gastrointestinal stromal tumors (GISTs) harboring KIT or PDGFRA mutations." (PMID 41559406, 2026). "While most gastrointestinal stromal tumors are driven by oncogenic mutations in KIT or PDGFRA, 10-15% exhibit functional loss of the succinate dehydrogenase (SDH) complex and genome-wide DNA hypermethylation." (PMID 42191879, 2026). "Gastrointestinal stromal tumors (GISTs) are mesenchymal tumors often driven by KIT or PDGFRA mutations." (PMID 40584566, 2025). "Mutations within the PDGFRA gene are associated with a spectrum of neoplasms, most notably including the clonal hypereosinophilia class of malignancies and gastrointestinal stromal tumors (GISTs)." (PMID 40336047, 2025). "The D842V platelet-derived growth factor receptor α (PDGFRA) mutation identifies a molecular subgroup of gastrointestinal stromal tumors (GISTs), primarily resistant to standard tyrosine kinase inhibitors and with an overall more indolent behavior." (PMID 39853981, 2025). "Variants in KIT and PDGFRA also point to a possible link between familial gastrointestinal stromal tumours and CRC." (PMID 40627234, 2025). "Avapritinib is a selective, type I PDGFRA-targeted TKI approved by the Food and Drug Administration30 for the treatment of adults with advanced gastrointestinal stromal tumors harboring PDGFRA exon 18 mutations, such as PDGFRA D842V31." (PMID 40819143, 2025). "Oncogenic mutations of EGFR gene are frequent in non-small cell lung cancer, and KIT or PDGFRA activating alterations are a hallmark of gastrointestinal stromal tumors." (PMID 40514442, 2025). "As the most common sarcomas, gastrointestinal stromal tumors (GISTs) are a diverse group of tumors that arise from mutually exclusive activating mutations in either KIT or PDGFRA." (PMID 40343114, 2025). "This study highlights Luteolin's potential as a dual inhibitor of PDGFRα T674I and c-Kit D816H, mutations associated with drugresistance in gastrointestinal stromal tumors (GISTs)." (PMID 39917220, 2024). "Avapritinib is a selective tyrosine kinase inhibitor (TKI) that has received FDA approval for the treatment of metastatic or unresectable gastrointestinal stromal tumors harboring a platelet-derived growth factor receptor α (PDGFRA) exon 18 mutation." (PMID 39272847, 2024). "Gastrointestinal stromal tumors (GISTs) are the most common mesenchymal tumors of the gastrointestinal tract, with proto-oncogene, receptor tyrosine kinase (c-kit), or PDGFRα mutations detected in around 85% of cases." (PMID 38612518, 2024). "PDGFRα is primarily known for its involvement in various cancers, especially gastrointestinal stromal tumors (GISTs), where mutations or dysregulation of PDGFRα play a significant role." (PMID 38607023, 2024). "Gastrointestinal stromal tumors (GIST) are rare mesenchymal tumors characterized by KIT or PDGFRA mutations." (PMID 37686582, 2023). "The latest avapritinib and ripretinib are effective and selective TKIs, which have been approved both internationally and in China for the treatment of PDGFRA 18 exon mutation and fourth‐line metastatic gastrointestinal stromal tumors, respectively." (PMID 37329178, 2023). "Familial gastrointestinal stromal tumors (GISTs) are mesenchymal tumors of the digestive tract caused by germline gain-of-function mutations in the KIT gene or platelet-derived growth factor receptor alpha gene (PDGFRA)." (PMID 37870660, 2023). "Most gastrointestinal stromal tumors are caused by protein kinases, particularly wild-type and mutant platelet-derived growth factor receptor A (PDGFRA) and KIT (GIST)." (PMID 37631077, 2023). "Approximately 8% of the gastrointestinal stromal tumors devoid of KIT/ PDGFRA mutations bear the BRAF mutation." (PMID 37454137, 2023). "Mutations in PDGFRα have been associated with several cancers including somatic and familial gastrointestinal stromal tumors, in addition to idiopathic hypereosinophilic syndrome." (PMID 36359362, 2022).
gastrointestinal stromal tumor (continued). "Gastrointestinal stromal tumors (GISTs) harboring mutations in the PDGFRA gene occur in only about 5–7% of patients." (PMID 36293105, 2022). "The aim of this study is to investigate the mutational status of c-KIT and PDGFRA, by PCR and sequencing, in 17 canine gastrointestinal stromal tumors." (PMID 35878393, 2022). "Platelet-derived growth factor receptor A (PDGFRA) mutations occur in approximately 10–15% of gastrointestinal stromal tumors (GISTs)." (PMID 36119525, 2022). "Somatic driver mutations in PDGFRA contribute to the development of glioma and gastrointestinal stromal tumours (GIST)." (PMID 35689379, 2022). "GISTs are heterogeneous tumors, including various molecular entities with usually mutually exclusive mutations of activated oncogenes, mainly KIT or platelet-derived growth factor-alpha (PDGFRA) mutations." (PMID 35646090, 2022). "Activating mutations in c-KIT and PDGFRA genes are considered the key molecular drivers of human gastrointestinal stromal tumors pathogenesis and are used to predict the response to Receptor tyrosine kinase inhibitors." (PMID 35878393, 2022). "Mutation on PDGFRA has been reported in gastrointestinal stromal tumors and in chronic myeloid leukemia." (PMID 35399006, 2022). "In conclusion, this study provides evidence for the presence of c-KIT and PDGFRA mutations in canine gastrointestinal stromal tumors and suggests a potential association of c-KIT mutation with the more aggressive biological behavior of the tumor." (PMID 35878393, 2022). "Gain-of-function mutations KIT and PDGFRA tyrosine kinases (TK) are responsible for between 85 and 90% of gastrointestinal stromal tumors (GIST), with the latter occurring only in approximately 5–10% of cases." (PMID 36293105, 2022). "Avapritinib was approved in 2020 by the FDA for gastrointestinal stromal tumors with a mutation in exon 18 PDGFRA (NAVIGATOR study), a multicenter, single-arm, open-label trial." (PMID 33419029, 2021). "Gastrointestinal stromal tumors (GISTs), the most widespread type of sarcoma, contain driver gene mutations predominantly of receptor tyrosine kinase and platelet-derived growth factor receptor alpha." (PMID 32251287, 2020). "PDGFRA plays a role in tumor progression, and mutations in PDGFRA have been associated with idiopathic hypereosinophilic syndrome 3, gastrointestinal stromal tumors 4, and several other cancers." (PMID 32226509, 2020). "Platelet Derived Growth Factor Receptor Alpha (PDGFRA) mutations occur in only about 5–7% of gastrointestinal stromal tumors (GIST), notably with alterations on exons 12/14/18." (PMID 32670260, 2020). "Instead, FDA-approved avapritinib (Ayvakit), another PDGFRα inhibitor, was investigated in clinical trials to treat patients with gastrointestinal stromal tumors (GISTs) presenting a PDGFRA D842V mutation, demonstrating a high response rate in 85% of patients." (PMID 32754598, 2020). "Crenolanib is a small molecule tyrosine kinase inhibitor with that is effective against PDGFR-α and presently in clinical trials for patients with gastrointestinal stromal tumors (GIST) in which PDGFRA activation mutations confer resistance to imatinab." (PMID 32411595, 2020). "The platelet-derived growth factor receptor A (PDGFRA) is a tyrosine kinase receptor that is frequently mutated in gastrointestinal stromal tumors." (PMID 32796636, 2020). "The majority of gastrointestinal stromal tumors (GISTs) are driven by a constitutively activating mutation in the KIT or PDGFRA (platelet-derived growth factor receptor alpha) receptor tyrosine kinase." (PMID 32198455, 2020). "Platelet-Derived Growth Factor Receptor Alpha (PDGFRA) mutations occur in approximately 5–7% of gastrointestinal stromal tumours (GIST)." (PMID 30778083, 2019). "Up to 85% of gastrointestinal stromal tumors (GIST) harbor mutually exclusive mutations in the KIT or the PDGFRA gene." (PMID 31124195, 2019).
gastrointestinal stromal tumor (continued). "Patients with metastatic KIT/PDGFRA wild-type succinate dehydrogenase–deficient gastrointestinal stromal tumors harboring succinate dehydrogenase subunit A mutations show a remarkable long survival." (PMID 31372201, 2019). "Activating mutations in PDGFRA have been identified in patients with gastrointestinal stromal tumors." (PMID 30791866, 2019). "Gastrointestinal stromal tumors (GISTs), a type of mesenchymal tumor in the gastrointestinal tract, are believed to be closely associated with PDGFRA and C-KIT mutations." (PMID 31647020, 2019). "Succinate dehydrogenase (SDH)-deficient gastrointestinal stromal tumors (GISTs) constitute a small KIT/PDGFRA-WT GIST subgroup featuring DNA methylation which, although pervasive, appears nevertheless not randomly distributed." (PMID 30616628, 2019). "Gastrointestinal stromal tumors (GISTs) are characterized by the presence of activating mutations in KIT or PDGFRα genes." (PMID 30472630, 2018). "The role of cKIT and PDGFRA mutations has been, most notably, investigated in gastrointestinal stromal tumors (GIST), where these two mutations are mutually exclusive." (PMID 29324814, 2018). "Mutations in the PDGFRA gene had been implicated in idiopathic hypereosinophilic syndrome, somatic and familial gastrointestinal stromal tumors, brain tumor and a variety of other cancers." (PMID 27903959, 2017). "In fact, it has been well documented that a significant proportion of gastrointestinal stromal tumors (GISTs) harbour also activating mutations of platelet-derived growth factor receptor a (PDGFRA)." (PMID 27738305, 2017). "Most gastrointestinal stromal tumors (GISTs) harbor mutually exclusive gain of function mutations in the receptor tyrosine kinase (RTK) KIT (70–80%) or in the related receptor PDGFRA (~10%)." (PMID 28768491, 2017). "Gastrointestinal stromal tumors (GISTs) are caused by the constitutive activation of KIT or platelet-derived growth factor receptor alpha (PDGFRA) mutations." (PMID 28487491, 2017). "Gastrointestinal stromal tumors (GISTs) with KIT or platelet-derived growth factor receptor alpha (PDGFRa) oncogenic driver gene mutations, respond to tyrosine kinase inhibitors (TKIs) including imatinib, sunitinib, and regorafenib." (PMID 29100343, 2017). "Despite known targeted therapeutic options in solid tumors (KIT or PDGFRA mutations in gastrointestinal stromal tumors), STS still lacks therapeutically relevant genetic alterations." (PMID 27016421, 2016). "The PDGFRA mutation is observed in approximately 7% of gastrointestinal stromal tumor, and 80% of the PDGFRA mutations are found in exon 18, which is located in the tyrosine kinase domain." (PMID 27105424, 2016). "Germline variants of FGFR3 and PDGFRA were also found in medulloblastoma and gastrointestinal stromal tumors, respectively." (PMID 27701467, 2016). "Among patients with gastrointestinal stromal tumors, seven percent cases harbors activating mutations in PDGFRα and targeted therapy inhibiting PDGFRα significantly prolongs survival of these patients." (PMID 25333264, 2014). "Acquired resistance to tyrosine kinase inhibitors (TKIs) in gastrointestinal stromal tumours (GISTs) is most commonly caused by secondary KIT or PDGFRA mutations." (PMID 25132955, 2014). "Gastrointestinal stromal tumors are rare soft tissue sarcomas that typically develop from mesenchymal cells with acquired gain-in-function mutations in KIT or PDGFRA oncogenes." (PMID 24159917, 2013). "The role of PDGFRA in cellular growth and proliferation is underlined by its contribution to the pathogenesis of gastrointestinal stromal tumours." (PMID 22144915, 2011). "Oncogenic point mutations in KIT or PDGFRA are recognized as the primary events responsible for the pathogenesis of most gastrointestinal stromal tumors (GIST), but additional genomic alterations are frequent and presumably required for tumor progression." (PMID 20470368, 2010).